TNF (tumor necrosis factor)
Diseases named in the same sentence as TNF in open-access papers (continued):
Sharing a sentence is not in itself a finding about the gene and the disease.
Granuloma (continued). "Granuloma formation at the site of infection is dependent upon pro-inflammatory TNF-α expression, and blocking TNF-α expression can result in downregulation of IFN-γ, IL-12, IL-10, IL-17, and nitric oxide production." (PMID 36144467, 2022). "The frequency of CD4+ and CD8+ T cells that were producing the cytokines TNF-α- and IFNγ from lung granulomas, thoracic LNs, and lung tissue homogenates were measured as part of our previous study for the SIV+ group as a whole." (PMID 35467372, 2022). "It was shown early in the investigation of the various roles of TNF that the maintenance of the protective granulomas in M. tuberculosis infection was dependent on the interaction of TNF with TNFR-1." (PMID 36358688, 2022). "TNF-α stimulates the migration of immune cells to the site of infection and is essential for the maintenance and formation of granulomas." (PMID 34150674, 2021). "Hematopoietic cell transplantation was the most successful treatment in this case series resulting in granuloma resolution; steroids, and TNF-α and IL-1R inhibitors were moderately effective." (PMID 35003119, 2021). "L-GSH supplementation was also able to modulate cytokines levels of IFN-γ, TNF-α, and IL-2 within in vitro granulomas treated with everolimus." (PMID 33966361, 2021). "These macrophages form clusters around the caseous zone of granulomas in patients with TB, and their presence depends on tumor necrosis factor (TNF)." (PMID 35008755, 2021). "The improved ability to control a BCG infection for the L-GSH group, when compared to the placebo group, also correlated with significant increases in the levels of IFN-γ and TNF-α in the supernatants of in vitro granulomas." (PMID 34150674, 2021). "TNF-α can also act as a coagulation inducer, being an important agent in the formation of granuloma." (PMID 34843474, 2021). "The role of TNF in S. mansoni egg-induced granulomas remains unresolved after two decades of studies in the murine model of schistosomiasis." (PMID 33465071, 2021). "The finding of granulomas is less frequent in patients taking anti-TNF, since granuloma formation is dependent on inflammatory cytokines and alpha-TNF." (PMID 34203639, 2021). "We revealed an upregulation of miR-889 by soluble TNF-α; adalimumab then reduced TNF-α levels and thus affected the expression of miR-889, resulting in granuloma destruction." (PMID 31992621, 2020). "Finally, the mathematical design of in-silico granulomas suggested that differences in drug binding kinetics and vascular permeability could explain the differential rates of TB reactivation associated with the different TNF-α-targeting biologics." (PMID 32069329, 2020). "Excessive leukotrienes promote TNF-α and Type I IFNs that result in increased necrotic cell death, granuloma caseation and cavity formation." (PMID 32849525, 2020). "Although the role of TNF--α is crucial for the formation of granuloma and enhanced killing of infected cells in the lungs during the primary infection, concentrations of TNF-α in CSF correlate with clinical correlation of TBM." (PMID 32937808, 2020). "AMs produce a range of pro-inflammatory cytokines, such as tumor necrosis factor-α (TNF-α), which drives granuloma formation in sarcoidosis." (PMID 32722050, 2020). "Altogether, we have shown that infection in elderly patients decreases granuloma formation and reduces the production of TNF-α and the formation of epithelioid cells and MGCs." (PMID 32411623, 2020). "Smoking is thought to trigger systemic increases in cytokines, such as IL-6, IL-1β, and TNF-α, which are critical in the formation of granulomas." (PMID 32872212, 2020). "Having selectively used CD4+ T-cell responders to PPD in this study, we intuitively expected that T cells would be mainly responsible of the late wave of TNF-α observed following granuloma formation." (PMID 32069329, 2020).
Granuloma (continued). "Our results also demonstrated the fact that the number of liver immature granulomas was basically consistent with the trend of TNF-α level at 4th, 8th and 12th week post-infection." (PMID 32176727, 2020). "Based on pathogenetic indications that tumor necrosis factor (TNF)-α is a central mediator of granuloma formation, adalimumab, targeting TNF-α, was employed in 6 patients as a third-line agent for severe/refractory chronic sarcoidosis." (PMID 32740881, 2020). "Inflammatory mediators such as interleukin-1α (IL-1α), TNF-α and IL-6 are recognized to be involved in the formation of the granuloma." (PMID 30917586, 2019). "These granulomas are further accompanied by increased production of the innate cytokines IL-1β, IL-6, and tumor necrosis factor (TNF), and enhanced phagocytic capacity of microglial cells." (PMID 30610193, 2019). "Using the ELISA technique, our results showed that the rats challenged with cotton pellet-induced granuloma had significantly elevated levels of the proinflammatory markers, IL-6 and TNF-α, as compared to normal control group (respectively)." (PMID 31263381, 2019). "In PCM, TNF is required for the persistence of well-formed granulomas and NO production and contrarily, it is highly induced in mice after in vivo challenge with F1." (PMID 31736892, 2019). "Extracellular bacteria grow more profusely (compare growth from 3 to 5 dpi in control and TNF-high granulomas), with a characteristic cording morphology." (PMID 31474371, 2019). "With this being said, TNF-α is an extremely important cytokine for the formation of granulomas in M. tb infection." (PMID 31888124, 2019). "In the granuloma model, the levels of NO, Tumor necrosis factor-α (TNF-α), interleukin IL-β, and interleukin IL-10 in serum were evaluated." (PMID 30823424, 2019). "IFN-γ expressed by helper and γδ T cells stimulates cell-mediated inflammation and induces macrophages to undergo autocrine and paracrine TNF-α signaling required for granuloma development." (PMID 31614819, 2019). "Their use is based on the blockage of TNF-α, which plays an important role in granulomas formation, development of phagosomes, activation and differentiation of macrophages, immune response against viral pathogens." (PMID 30732563, 2019). "IFN-γ induces P. brasiliensis-infected macrophages to secrete TNF-α, required for the development and persistence of well-formed granulomas, and NO, which plays a well-documented role in fungal clearance." (PMID 31425553, 2019). "T cell-derived TNF is required for the formation of granulomas, but to sustain the protective immunity against M. tuberculosis, both T cell- and macrophage-derived TNF molecules are necessary." (PMID 31787969, 2019). "Altogether, these results suggest that inhibition of TNF-α alters macrophage polarization and cytokine release in Mtb-induced granulomas." (PMID 31475008, 2019). "Decreasing the size of granuloma tissue, it is well correlated with decreased pro-inflammatory cytokines levels (e.g., TNF-α, and IL-1β), as well as an increased level of IL-10." (PMID 30823424, 2019). "Mtb-specific CD4 T cell production of the Th1 cytokines IFN-γ and TNF-α is important for activating macrophages and promoting formation of granulomas in the lung for containment of Mtb." (PMID 31497018, 2019). "We observed a significant decrease in the levels of TNF-α in EMB-treated granulomas at both 8 and 15 days post-infection." (PMID 30258443, 2018). "ICAM-1 is found at elevated levels within egg-evoked granulomas and TNF-α drives the host immune response to schistosome eggs." (PMID 30059006, 2018). "TNF-α is a Th1 cytokine known to play a key role in the formation of granuloma for the containment and protection against Mycobacterium." (PMID 31086619, 2018). "TNF-α, a critical pro-inflammatory cytokine is an imperative early incident that leads to granuloma formation and help in providing protective host immune responses." (PMID 30395609, 2018).
Granuloma (continued). "Evaluation of the cytokine expression in granulomas associated with different clinical and CBCT data showed a significant relationship only between high levels of TNF-α and small <5 mm AP lesions (p=0.017)." (PMID 29898177, 2018). "The production of cytokines, such as IFN-γ and TNF-α, is fundamental in the formation and maintenance of granulomas and in the control of the disease." (PMID 29543912, 2018). "L-GSH treatment of BCG granulomas resulted in a significant reduction in the levels of proinflammatory cytokines such as IL-6 and TNF-α, and a decrease in oxidative stress." (PMID 29494546, 2018). "Comparison between the pro- and anti-inflammatory cytokines in granulomas revealed that IL-4 expression was significantly higher when compared with IL-6 (p=0.001) and TNF-α (p=0.001)." (PMID 29898177, 2018). "In this study, we also analyzed the effect of TNF-α blockade on the modulation of Th1, Th17, and regulatory T cytokines both in the granuloma model and after the stimulation with soluble antigens." (PMID 29543912, 2018). "In this study using in vitro granuloma model, we observed that TNF-α blockade not only blocks its bioavailability, with significant modulation of granuloma, but also significantly reduces the levels of IL-12p40, IFN-γ, IL-17 and IL-10." (PMID 29543912, 2018). "The messenger RNAs of proinflammatory cytokines TNF-α, IL-1β, and IL-6, which initiate the fibrotic process, have been demonstrated in macrophages located at the periphery of granulomas." (PMID 30037796, 2018). "Neutrophil recruitment regulated by the TNF/IL-8 axis is essential for the establishment and maintenance of granulomas, which provides protective immunity to the host during mycobacterial infections." (PMID 29698503, 2018). "By contrast, TNFα immunostaining in solid granulomas seemed to be more diffuse and in general lower compared to necrotic granulomas." (PMID 30018616, 2018). "TNF-α, being an immunomodulatory cytokine, appears to retain stable levels once a granuloma has been established amongst healthy individuals." (PMID 29494546, 2018). "Several pro-inflammatory cytokines such as tumor necrosis factor (TNF)-α, interferon (IFN)-γ, IL-6, IL-12 and IL-18 have been associated with granuloma formation on large vessels." (PMID 28400869, 2017). "Each macaque was evaluated for reactivation which was strictly defined here as dissemination, determined by the appearance of at least one new granuloma in lungs or extrapulmonary sites by PET CT during anti-TNF antibody treatment." (PMID 27379816, 2016). "Dynamic granulomas had higher CFU/CEQ ratios (i.e., less bacterial killing) than stable granulomas among all animals undergoing TNF neutralization." (PMID 27379816, 2016). "At necropsy, macaques that developed new granulomas during TNF neutralization had greater disease pathology and higher total bacterial burden in lungs as well as within individual granulomas and lymph nodes." (PMID 27379816, 2016). "Differential cytokine expression was seen in granulomas of the lungs compared to those of the tracheobronchial lymph nodes for all cytokines examined with the exception of TNF-α." (PMID 27902779, 2016). "The different capacities of R and S morphotypes to kill macrophages and induce the formation of granulomas, and the secretion of IL-6 and TNF-α were determined." (PMID 27757105, 2016). "In this M. tb-induced in vitro granuloma model, dormant M. tb can be reactivated by adding anti-TNF-α monoclonal antibody." (PMID 27489303, 2016). "TNF-α is also required for the formation and maintenance of granulomas and can even influence the production of chemokines during M. tb challenge." (PMID 27050308, 2016). "These responses stimulate cells to secrete a variety of cytokines and chemokines (e.g. IFN-γ, IL-12, TNF-α, IL-8) that induce migration and close interaction of immune cells, leading to granuloma formation." (PMID 27489303, 2016).
Granuloma (continued). "For TNF-α, expression was greater in tracheobronchial lymph node granulomas, but less in caudal mediastinal lymph granulomas compared to uninfected caudal mediastinal lymph nodes." (PMID 27902779, 2016). "Surprisingly, T cells producing single cytokines were most frequently observed in the granulomas, particularly TNF and IL-17." (PMID 25611466, 2015). "In sarcoidosis, alveolar macrophage-derived TNF-α participates in the induction and maintenance of granulomas and high levels of TNF-α released from alveolar macrophages seem to correlate with disease progression." (PMID 25866481, 2015). "Administration of recombinant murine TNF-α to mice with chronic schistosomal infection has increased the size of liver granulomas, and injections of polyclonal anti-TNF-α into acutely infected mice have suppressed the size of developing granulomas." (PMID 25582427, 2015). "Although the responses generally overlapped, sterile granulomas had modestly higher frequencies of T cells making IL-17, TNF and any of T-1 (IFN-γ, IL-2, or TNF) and/or T-17 (IL-17) cytokines than non-sterile granulomas." (PMID 25611466, 2015). "In experimental models, the selective neutralization of TNF-α inhibits the formation of granulomas and reduces the microbicidal activity of macrophages and NK cells." (PMID 26273486, 2015). "Granuloma group T1, which was vaccinated with an antigen that is specific to early stage TB infection and given anti-TNF antibodies, had 50% of granulomas disseminate, all of which were contained when anti-TNF was spared (Group 1)." (PMID 26779136, 2015). "TNF-α and IL-6 are thought to play significant roles in S. japonicum egg induced granuloma formation." (PMID 25582427, 2015). "Compared to Group 0, adding anti-TNF antibodies at day 150 to induce reactivation (Group T0) increased the number of disseminating granulomas from 0 to 85%." (PMID 26779136, 2015). "Both IFN-γ and TNF-α present near the local concentrations area in pleural fluid of TB, which are useful for the bacilli elimination and granuloma formation." (PMID 24984978, 2014). "Granuloma formation as well as the local immune response played by phagocytic cells and sustained granulomatous inflammation depend on TNF-α synthesis and are necessary to restrict fungal growth and dissemination." (PMID 24743161, 2014). "It has shown that during MTB infection, TNF-α is produced transiently and focally by granulomas in response to mycobacterial challenge." (PMID 24554385, 2014). "Taken together, these results suggest that the parameters in the signaling group are establishing the most beneficial response to the concentrations of TNF-α and IL-10, which is critical to the control of the immune response occurring in a granuloma." (PMID 23869227, 2013). "In human livers with hepatic AE, the mRNAs of pro-inflammatory cytokines, interleukin (IL)-1β, IL-6, and TNF-α have been found in macrophages located at the periphery of granulomas, in those areas which were shown to be at the initiation of fibrogenesis." (PMID 23405141, 2013). "Since Mtb -induced apoptosis in is not mediated by the production of TNF-α, in our in vitro granuloma model, we did not observe any change in the number of apoptotic cells following treatment of granulomas with anti-TNF mAb." (PMID 23308269, 2013). "The balance of TNF-α and IL-10 concentrations in a granuloma presents a possible new avenue for treatment strategies." (PMID 23869227, 2013). "Blood monocytes that arrive then undergo differentiation into exudates macrophages which in turn releases factors such as tumor necrosis factor-α (TNF-α) and interleukin-1β (IL-1β), which enhances the formation of a granuloma." (PMID 23533794, 2013). "In order to determine if Mtb caused apoptosis, PBMCs were infected with Mtb H37Rv and apoptosis was determined in uninfected PBMCs and after treatment of granulomas with IgG and anti-TNFα mAb." (PMID 23308269, 2013).
Granuloma (continued). "Removal of TNF-α during Mtb infection leads to a range of outcomes, such as unstructured granulomas, and large increases in total bacterial burden." (PMID 23869227, 2013). "A diverse array of cytokines has been shown to influence the formulation and maintenance of Mtb granulomas, including TNFα and IL-6." (PMID 23577168, 2013). "IL-4 is a Th2 cytokine which increases TNF-α toxicity thereby aggravating tissue damage and inducing fibrosis of granuloma leading to enhanced immunopathology." (PMID 24147054, 2013). "TNFα is a pivotal mediator of granuloma formation and maintenance, and is thought to play an important role in sarcoidosis pathogenesis." (PMID 22513006, 2012). "Using a commercial kit to detect typical Th1/Th2 cytokines, we compared the levels of IFN-γ, TNF-α, IL-2, IL-4, and IL-5 in lung homogenates 14 days after granuloma induction and in serum samples collected 1, 5, 14 and 18 days after granuloma induction." (PMID 22013486, 2012). "IP-10 is produced by monocytes-macrophages after IFN-γ and TNF-α stimulation and induces chemotaxis on monocytes and lymphocytes in the formation of granulomas." (PMID 23144772, 2012). "The induction of IFNγ and IL-12 and the depletion of IL-4 producing NK cells has been attributed to TDM as well as a role, along with IL-6 and TNFα, in stable granuloma formation." (PMID 22738036, 2012). "Lymphocytes recruitment was focused and predominantly occupied central areas of granulomas in reactivating WT mice but was unorganized in reactivating Tm-TNF mice." (PMID 22132068, 2011). "It is clear that macrophage distribution correlated strongly with iNOS induction where, in WT mice it was localized on the periphery of established granulomas but randomly distributed in Tm-TNF mice at 322 days post-infection." (PMID 22132068, 2011). "This is evidenced by the development of true latency, caseous granulomas and differences in the response to TNF blockade." (PMID 21789257, 2011). "There was significantly more TNF-α in both macrophages (p = 0.003) and granulomas (p≤0.001) in biopsies classed as being in T1R." (PMID 22180790, 2011). "In sarcoidosis, TNF-alpha participates in the induction and maintenance of granulomas and high levels of TNF-alpha seems to correlate with systemic disease progression." (PMID 21603192, 2011). "This cascade culminates in the expression of many NF-κB-inducible genes, including CCL2, IL1B, IL12, IL18 and TNF, causing natural killer (NK) and T cells to release IFN-γ and TNF-α, which ultimately results in granuloma formation." (PMID 22182502, 2011). "Previously, we proposed that Tm-TNF alone was sufficient to develop distinct granulomas during respiratory M. tuberculosis infection, but referred to the diminished bactericidal capacity of such granulomatous structures." (PMID 22132068, 2011). "Tumor necrosis factor-alpha (TNF-α) is considered the pivotal factor in the formation of granulomas by mediating inflammation and cellular immune response among the cytokines involved." (PMID 21929754, 2011). "This type of granulomas is associated with a TH1 immune response and is dominated by interleukin 12 (IL-12), interferon-γ (IFN-γ), IL-2 and tumor necrosis factor alpha (TNF-α) resulting in macrophage activation and a strong cell-mediated immunity." (PMID 20507624, 2010). "To elucidate the mechanisms by which availability of TNF in a granuloma is controlled, we focus on TNF interactions with immune cells that comprise a granuloma." (PMID 20463877, 2010). "Granuloma formation depends entirely on TNF production by the infected macrophages and T cells, as well as the integrity of all ligands and receptors of the TNF family." (PMID 20886087, 2010). "Further, numerous reports have begun to reveal the role of TNF in granuloma formation as well as in maintenance of granulomas in latent TB." (PMID 20463877, 2010).